CRP (C-reactive protein)
Diseases named in the same sentence as CRP in open-access papers (continued):
Sharing a sentence is not in itself a finding about the gene and the disease.
pancreatic cancer (continued). "Nevertheless, in several small hospital-based case-control studies, CRP concentrations were significantly higher in pancreatic cancer cases compared to chronic pancreatitis patients or controls." (PMID 31464604, 2019). "NLR and high CRP levels proved independent predictors of overall survival in patients receiving palliative chemotherapy for pancreas carcinoma with advanced or metastatic disease." (PMID 31717722, 2019). "Despite the inflammatory changes associated with chronic pancreatitis, the inflammatory markers CRP and IL-6 remain lower than stage II–IV pancreatic cancer patients." (PMID 28335509, 2017). "Because of this limitation, we will evaluate the prognostic value of other common markers of systemic inflammation, including CRP and IL-6, in patients with pancreatic cancer and their correlation with serum LDH levels in future studies." (PMID 28345594, 2017). "For overall survival, the optimal cutoff point of the CRP/Alb ratio for stratifying patients with advanced pancreatic cancer (PC) was 0.54." (PMID 27344157, 2016). "A strong positive correlation between high CRP and high IL-6 levels was shown in advanced pancreatic cancer." (PMID 26717416, 2015). "In 102 unresctable pancreatic cancer patients elevated C-reactive protein at the time of diagnosis was found to be an independent poor prognostic factor." (PMID 23530866, 2013). "The third patient with pancreatic cancer had 24 treatments during 90 days and CRP was increased from 15 mg/L to 89 mg/L." (PMID 22963460, 2012). "Preoperative and postoperative CRP levels of >10 mg l−1 are independent indicators predictive of poor prognosis of patients with pancreatic carcinoma." (PMID 17667928, 2007). "Additionally, studies of older patients with pancreatic cancer have reported that those with a low CRP/albumin ratio exhibit good treatment responses." (PMID 39870769, 2025). "We compared basic clinical data, including age, height, weight, BMI, and biochemical features, such as white blood count and platelets (PLT), erythrocytes (ERY), CRP, and Ca 19-9 counts, between patients with pancreatic cancer and neuroendocrine tumors and healthy controls." (PMID 40699634, 2025). "In pancreatic cancer, blood CRP levels were specially related to tumor size." (PMID 37415393, 2025). "These study results provide unique insights into individual research findings, with a focus on the hypothesis that PF and the CRP/Alb ratio are prognostic factors for pancreatic cancer." (PMID 38496751, 2024). "In addition, hepatocyte growth factor (HGF), fibrinogen, and inflammatory markers such as C-reactive protein (CRP) and interleukin-6 (IL6) have been linked to pancreatic cancer instances." (PMID 39200847, 2024). "However, CRP showed all other systemic inflammatory responses, and it was difficult to consider it as a specific marker for pancreatic cancer." (PMID 39857647, 2024). "Furthermore, CRP is an important prognostic indicator in a number of malignancies, including pancreatic cancer, urological cancer, hepatocellular carcinoma, and NSCLC." (PMID 38803531, 2024). "Clinicopathological features of 250 pancreatic carcinoma patients stratified by PF and CRP/Alb." (PMID 38496751, 2024). "Therefore, the CRP/Alb ratio demonstrates promise as an inflammatory marker, bearing significance for the clinical prognosis of those with pancreatic carcinoma." (PMID 38496751, 2024). "However, in pancreatic cancer studies, the cut-off values for CRP have varied and many studies involved only small-scale patient samples or only patients with advanced disease." (PMID 33437015, 2021). "In addition, there was a significant correlation between serum CXCL8 concentration and CRP levels as well as with nodal involvement in pancreatic cancer patients." (PMID 34680333, 2021). "Importantly, it has been confirmed that the preoperative level of serum CRP is related to the prognosis of hepatocellular carcinoma and pancreatic cancer." (PMID 34720749, 2021).
pancreatic cancer (continued). "Furthermore, there is strong positive correlation between CRP and IL-6 levels found in advanced pancreatic cancer patients." (PMID 29619344, 2018). "Indeed, the prognostic value of CRP has been already demonstrated for malignant pleural mesothelioma, lung, breast and pancreatic cancer for instance." (PMID 28514756, 2017). "Accordingly, it was observed that markers of systemic inflammation (IL-6, CRP) correlated with the increased expression of ubiquitin in skeletal muscle biopsies from cachetic patients with pancreatic cancer, and this increase correlated with the degree of weight loss." (PMID 26856534, 2016). "A recent study showed that weight loss (>10% weight loss), reduced food intake (<1500 kcal/day), and evidence of systemic inflammation [C-reactive protein (CRP) > 10 mg/L] identified pancreatic cancer patients with reduced subjective and objective functional ability." (PMID 24624094, 2014). "CRP is also a strong prognostic predictor in many cancers, including metastatic renal cell carcinoma, advanced pancreatic cancer, gastric cancer, breast cancer, colorectal cancer, inoperative non-small cell lung cancer, prostate cancer, pancreatic cancer, and esophageal cancer." (PMID 24130817, 2013). "Univariate Cox model analysis further demonstrated that PS, clinical stage, CRP levels, and CEC levels are all associated with the survival of pancreatic carcinoma patients, while multivariate Cox analysis showed that CEC and IL-10 levels are strongly associated with survival." (PMID 22731825, 2012). "Furthermore, the combination of the CRP/Alb ratio and the PF could increase the precision of prognosis prediction in pancreatic carcinoma patients." (PMID 38496751, 2024). "PF concentration is a convenient, rapid, and noninvasive biomarker, and its combination with the CRP/Alb ratio could significantly enhance the accuracy of prognosis prediction in pancreatic carcinoma patients, especially those with the most common histological subtype of PDAC." (PMID 38496751, 2024). "However, the potential of the preoperative CRP/Alb to function as a prognostic indicator in individuals with pancreatic carcinoma and whether its prognostic efficacy surpasses that of other inflammatory prognostic factors are unclear." (PMID 38496751, 2024). "Although CRP is a very common inflammation marker, in the context of our review, we only found two reported studies that fit our primary inclusion criteria of demonstrating usefulness in the clinic related to pancreatic cancer outcomes; and they had different results." (PMID 37181043, 2023). "Therefore, the CAR, a combined pattern of both CRP and albumin, may reveal the outcome of pancreatic cancer in a better way." (PMID 28592881, 2017). "Although the level of CRP may be associated with prognosis, it was not a routine test at the diagnosis of pancreatic cancer." (PMID 28678832, 2017). "Previous studies have demonstrated a relationship between CRP levels and the effectiveness of IRI-based regimens for advanced pancreatic cancer treatment." (PMID 39870769, 2025). "Recently, a new index, C-NLR, which consists of both CRP and neutrophil-to-lymphocyte ratio (NLR), has been proposed, and its prognostic significance was initially validated in patients with pancreatic cancer after pancreatic resection." (PMID 38233747, 2024). "Currently, a novel combination indicator, C-NLR, consisting of CRP and NLR, has been proposed and confirmed to be related to the poor prognosis of pancreatic cancer patients." (PMID 38233747, 2024). "Based on the cutoff value (> 0.18) used, our research findings indicate that among 250 pancreatic cancer patients, even within the PADC subgroup, an elevated CRP/Alb ratio signifies a shorter OS." (PMID 38496751, 2024). "In pancreatic cancer, a positive correlation has been observed between high PTX3 expression and inflammatory markers, including serum CRP and IL-6 levels." (PMID 39594709, 2024).
pancreatic cancer (continued). "The role of several prognostic indicators, such as the C-reactive protein/albumin (CRP/Alb) ratio and neutrophil/lymphocyte ratio (NLR), in the occurrence and development of pancreatic carcinoma has been confirmed." (PMID 38496751, 2024). "The ratio of C-reactive protein to lymphocytes (CLR) plays a key role in the prognosis of tumors, pancreatic cancer, colorectal cancer, and other related diseases, but there is no study on patients with aSAH." (PMID 35769371, 2022). "This trait of sPD-L1 has been described in pancreatic cancer patients and HCC patients where dichotomized patients groups with high and low CRP values were compared." (PMID 35184226, 2022). "We found these methylation-predicted CRP Scores to be moderately correlated with log-CRP and log-IL6 in the controls of a previously published pancreatic cancer dataset." (PMID 34915912, 2021). "This retrospective study explored CRP, CA19-9, and routine laboratory values as preoperative prognostic factors in pancreatic cancer patients." (PMID 33437015, 2021). "Investigating CRP and CA19-9 on operated NAT patients is especially interesting, adding new valuable information to pancreatic cancer research." (PMID 33437015, 2021). "This study revealed that the NLR was an independent prognostic factor in patients with unresectable pancreatic cancer, and superior to the GPS, modified GPS, PLR, CRP/Alb ratio, and PNI as the prognostic indicators." (PMID 33127996, 2020). "In this study, we addressed the prognostic significance of CRP and NLR in patients with pancreatic cancer by comparing various factors in uni- and multivariate analyses." (PMID 31717722, 2019). "However, few serum markers of chronic inflammation have been investigated in relation to CP and pancreatic cancer diagnosis (mainly CRP and cytokines such as Interleukin-6 (IL-6) and Tumour Necrosis Factors (TNF-α)), partially because CP may elevate pancreatic enzymes instead." (PMID 31464604, 2019). "Elevation of other serum proteins such as lactate dehydrogenase (LDH), C-reactive protein (CRP), and interleukin 6 (IL-6) also portends worse outcome of pancreatic cancer patients." (PMID 28335509, 2017). "In our study, we observed that CK19 mRNA expression was elevated exclusively in the serum of pancreatic cancer patients and was positively correlated with systemic inflammation, as indicated by increased WBC and CRP levels, two commonly used clinical inflammatory markers." (PMID 40699634, 2025). "Furthermore, CK19 overexpression was found to be positively correlated with inflammatory markers, specifically C-reactive protein (CRP) and WBC, in patients with pancreatic cancer." (PMID 40699634, 2025). "This study was designed to compare various blood biomarkers, such as neutrophil/lymphocyte ratio (NLR), lymphocyte/monocyte ratio (LMR), platelet/lymphocyte ratio (PLR), C-reactive protein (CRP), albumin (Alb), plasma fibrinogen (PF), and CRP/Alb in patients with pancreatic carcinoma." (PMID 38496751, 2024). "Second, some potential prognostic markers of pancreatic cancer like c-reactive protein were not considered in the model because they were not routine preoperative tests in our institution." (PMID 37051547, 2023). "Pre-operative pancreatic cancer patients who had cachexia and elevated CRP had an increase in serum C3a compared to non-cachectic pancreatic cancer patients." (PMID 38022578, 2023). "Platelet-to-lymphocyte ratio (PLR), neutrophil-to-lymphocyte ratio (NLR), and C-reactive protein (CRP), which are inflammatory biomarkers extracted from the peripheral blood, have shown predictive significance in patients with gastric cancer, pancreatic cancer, and renal cell carcinoma." (PMID 35558519, 2022). "Moreover, more recent reports have revealed that NLR, CRP-to-lymphocyte ratio (CLR), CAR, and GNRI play a critical predictive role in the incidence of POCs in pancreatic cancer." (PMID 36547189, 2022).
pancreatic cancer (continued). "Although previous studies demonstrated that elevated C-reactive protein to albumin ratio (CAR) predicted poor prognosis in various solid tumors, little was known about the prognostic value of CAR in patients with advanced pancreatic cancer (APC)." (PMID 28592881, 2017). "The modified Glasgow prognostic score and C-reactive protein (CRP) levels are valuable and commonly used markers of systemic inflammation, which correlate with the prognosis of numerous human cancers, including pancreatic cancer." (PMID 28345594, 2017). "A possible explanation for the apparent discrepancy is that pancreatic cancer patients with high CRP may not have been selected for GnP therapy, i.e., there could be selection bias in our study." (PMID 34260659, 2021). "Another case-control study nested in the European Prospective Investigation into Cancer and Nutrition (EPIC) cohort did also not find an association between pre-diagnostic circulating CRP, interleukin-6 (IL-6), tumour necrosis factors (TNF-α) and pancreatic cancer risk." (PMID 31464604, 2019). "The lack of other established inflammatory biomarkers such as C-reactive protein may result in residual confounding on the observed association between HAA ratio and risk of pancreatic cancer." (PMID 29734388, 2018). "However, the role of the CRP/Alb ratio in patients with advanced pancreatic cancer has not previously been elucidated." (PMID 27344157, 2016). "Several studies have shown how systemic inflammatory markers [C-reactive protein (CRP) and neutrophil–lymphocyte ratio (NLR)] may indicate a poor prognosis in many cancers (esophageal, stomach, colon, liver, renal, prostatic, ovarian, skin and pancreatic cancer)." (PMID 37504371, 2023). "However, the role of the CRP/Alb ratio in advanced pancreatic cancer (PC) has not been examined." (PMID 27344157, 2016).
Cachexia (150 papers, 2009 to 2026). Severe weight loss, wasting of muscle, loss of appetite, and general debility related to a chronic disease. "Although inflammatory markers such as IL-6 and CRP are mechanistically linked to cachexia and immune dysregulation, their inconsistent reporting across studies restricted meta-analytic synthesis." (PMID 40940861, 2025). "Severe weight loss is a substantial indicator of cachexia, but hemoglobin and CRP are essential for evaluating metabolic dysfunction, which can trigger weight loss." (PMID 41429072, 2025). "CAR, a well‐established inflammation‐nutrition index, reflects systemic inflammatory burden (via CRP) and hepatic synthetic function, while Cr quantifies muscle catabolism, a hallmark of cachexia progression." (PMID 41216846, 2025). "In another study, >54 appeared to identify risk of cachexia among patients with various hematologic malignancies, whereas a third study reported CRP > 10 was significantly associated with cachexia (p = 0.020)." (PMID 39001427, 2024). "Cancer cachexia is associated with systemic inflammation, and CRP levels correlate with shorter survival in patients with advanced cancer." (PMID 38438534, 2024). "Cut-offs of 10 mg/L for CRP in cancer cachexia typically yield significant relationships of CRP with a reduced lean mass and an increased loss of lean mass." (PMID 37906352, 2023). "Cancer cachexia is associated with alterations in hemoglobin, albumin, and C-Reactive Protein (CRP) levels." (PMID 38067294, 2023). "Regarding biomarkers, cachexia was associated with higher CRP, blood urea nitrogen and BNP and lower albumin, haemoglobin and haematocrit levels." (PMID 37434419, 2023). "Among the soluble immune mediators we detected that were associated with cachexia, the combination of cachexia and CRP, PTX‐3, or OPN expression levels were each associated with patient prognosis." (PMID 37712645, 2023). "Increased serum levels of interleukin-6 (IL-6) or C-reactive protein (CRP) are observed in cancer-induced cachexia patients, and these cytokines are even used as diagnostic markers for cancer-induced cachexia." (PMID 37240117, 2023). "Levels of proinflammatory cytokines (e.g., IL-6 and CRP) were also higher in the serum of cachectic patients than in the other two groups, thereby indicating that cachexia was associated with a highly inflammatory environment." (PMID 36973755, 2023). "The biological markers linked with cachexia include elevated C-reactive protein (CRP) and low serum albumin." (PMID 35888685, 2022). "The underlying inflammation in cachexia is recognized not only by higher levels of C-reactive protein (CRP) or low albumin, but a plethora of inflammatory proteins appears also to be altered in this syndrome." (PMID 35174197, 2021). "As such, cachexia is generally associated with increased levels of inflammatory molecules such as CRP, TNF-α, IL-6, and IL-8." (PMID 34830921, 2021). "In patients with CKD, cachexia was not only associated with elevated levels of CRP, but also increased fibrinogen, and reduced cross-sectional area (CSA) of muscle fibers and fat mass." (PMID 33329046, 2020). "Yet, routine laboratory parameters, such as C-reactive protein, hemoglobin, albumin and cholinesterase, have also been implicated in patients with cachexia." (PMID 31717736, 2019). "Both weight loss and the adverse effects of cachexia such as fatigue and performance status have been documented associated with systemic inflammatory response and CRP has in several studies and reviews proved to be an independent marker for survival." (PMID 21934689, 2011). "The patients had high CRP and IL-6 levels and low serum albumin levels, which are part of the suggested diagnostic criteria for cachexia, acknowledging that CRP and IL-6 mainly are markers of inflammation." (PMID 21483870, 2011). "Additionally, it has been shown that a high CRP level at the time of MM diagnosis is a factor increasing the risk of cachexia during treatment." (PMID 40115011, 2025).